EZR (ezrin)
Diseases named in the same sentence as EZR in open-access papers (continued):
Sharing a sentence is not in itself a finding about the gene and the disease.
tumor (continued). "The oncogenic potential of phosphorylated ezrin includes its ability to serve as an important topological organizer of specialized membrane domains to enable potent oncogenic signaling functions in tumor cells." (PMID 33960104, 2022). "Taken together, ezrin may play a key role in the plasma membrane localization of P-gp at the acidic tumor microenvironment, leading to an acquired MDR in a variety of cancer cells." (PMID 33974673, 2021). "In general, ezrin expression followed a similar pattern to vimentin throughout the passages, but with a more selective expression pattern according to the type of primary tumor." (PMID 34198671, 2021). "On the other hand, ezrin acts as a linker between the cytoskeleton and the plasma membrane and plays a role in the maintenance of the SG acinar cell architecture, cell polarity, and cell migration, contributing to the immune response and tumor progression." (PMID 34502121, 2021). "Besides functioning as a cytoskeletal organizer, Ezrin also plays a significant role in tumor signal transduction." (PMID 34485151, 2021). "The inhibition of ezrin greatly impairs the phagocytic capacity of tumour cells." (PMID 34332531, 2021). "The statistical analysis revealed significant relation between ezrin expression and tumor grade." (PMID 32334457, 2020). "However, other factors, including diagnosis time, tumor size, therapeutic treatment, and larger sample size should be considered to validate the correlation between Ezrin and Ewing sarcoma clinical outcomes." (PMID 33240887, 2020). "Studies of the role of ezrin in cancer have focused primarily on cancer cells themselves, whereas its role in tumor microenvironment-resident or infiltrating cells remains largely unknown." (PMID 33086476, 2020). "In light of these data, Ezrin represents a key regulator of tumor metastasis progression for its ability to regulate cell migration promoting EMT and to enhance the invasion capability through up-regulation MMP-2 and MMP-9 transcriptional and translational levels via the AKT signalling pathway." (PMID 33003361, 2020). "In addition, shNFIX-U87 cells with replenishment of Ezrin promoted the tumor malignant growth in brain of nude mice when compared with the control group." (PMID 32291386, 2020). "Therefore, the activation of Ezrin proteins facilitates the process of tumor progression and invasion." (PMID 33240887, 2020). "The focal adhesion structures were, in most cases, hardly identifiable in clinical specimens; however, close observations of immunofluorescent staining validated the co-localizations of FAK and five protein antigens (GRB7, FLNA, HSP90, PABPC1, and EZR) in these clinical tumor tissues." (PMID 33067514, 2020). "Additionally, macrophage ezrin contributes to the secretion of factors that stimulate tumor cell migration, invasion, and clonogenic growth." (PMID 33086476, 2020). "The molecular characteristics of the ezrin protein may be important during tumor progression; however, the clinical significance of these characteristics in human cancer requires clarification." (PMID 32334457, 2020). "Finally, we determined that LGALS3, CD44, FN1 and EZR were upregulated in both tumour and host stromal datasets." (PMID 32493768, 2020). "Here, we investigated the specific role of ezrin on macrophage communication with tumor cells." (PMID 33086476, 2020). "Furthermore, similar patterns of the protein levels of NFIX and Ezrin in orthotopic tumor were observed compared with that of in vitro U87 cells." (PMID 32291386, 2020). "Moreover, IHC staining found that the Ezrin-depleted tumour tissues had reduced numbers of Ki67-positive cells, whereas the Ezrin overexpressed group had higher Ki67 proliferation indexes." (PMID 30804430, 2019).
tumor (continued). "We observed a significant reduction in migration and invasion capacity of cancer cells in tumor-draining inguinal lymph node metastases following pharmacological inhibition of ezrin, with a concomitant decrease in metastatic burden in the draining axillary node." (PMID 30678714, 2019). "Ceramide-PP1α-mediated ezrin dephosphorylation is blocked in cancer cells by the widely used anti-tumour agent cisplatin, which also induces an elevation in the activity of the ceramide producing enzyme acid sphingomyelinase, and its redistribution to the plasma membrane." (PMID 31382374, 2019). "Ezrin plays a critical role in epithelial morphology, adhesion, and migration - all key events that contribute to the invasive phenotype of cancer cells during tumor progression." (PMID 30678714, 2019). "In addition, our study connects the interaction between Ezrin and AKT pathway to the promotion of BC cell behaviour associated with tumour progression." (PMID 30804430, 2019). "Ezrin, a membrane-cytoskeleton linker, plays a major role in promoting tumor progression." (PMID 31886273, 2019). "The overexpression of DCAF13, EZR, and MRPL13 in patients were associated with lower survival, which reveals that these genes might be associated with tumor invasion, progression and poor prognosis." (PMID 30881302, 2019). "We next examined whether treatment with the ezrin inhibitor would reduce tumor colonization and metastatic burden in the distal node (axillary) and lungs in an orthotopic mammary fat pad tumor engraftment model." (PMID 30678714, 2019). "Our findings demonstrate that the tumor ezrin level act as an independent biomarker in predicting relapse and provide a rationale for therapeutic targeting of ezrin to reduce the metastatic capacity of cancer cells in high-risk BC patients with elevated ezrin expression." (PMID 30678714, 2019). "All high-grade tumor patients were found to have high expression of ezrin." (PMID 30754703, 2019). "To ascertain whether our observations in cell lines also hold true for human specimens, we investigated tumour cells from liquid-phase biopsies of cancer patients for the presence of ezrin caps or spots." (PMID 29491397, 2018). "Aberrant expression of Ezrin and E-cadherin play an important role in tumor invasion." (PMID 29587669, 2018). "This is important to consider as it is unclear whether ezrin expression patterns may change in response to therapy or with tumor progression." (PMID 28246524, 2017). "Among them, vimentin and ezrin, which are known to be involved in the regulation of metastasis, were down-regulated under the treatment of tachyplesin I, suggesting that cytoskeleton are influenced by tachyplesin I, thus contributes to its anti-tumor activity." (PMID 28106765, 2017). "Ezrin expression was detected in 72% (38/53) of tumor samples." (PMID 28246524, 2017). "Our data show that ezrin is expressed in the majority of EWS tumor samples." (PMID 28246524, 2017). "Expression of Ezrin may be upregulated in cancer, and most probably phosphorylation of Ezrin is upregulated, which is shown to play an important role in tumor cell differentiation and metastasis." (PMID 28298808, 2017). "While we did not observe any significant associations between high and low ezrin intensity groups and known EWS prognostic factors (e.g., age, stage, tumor size, and primary site) it is possible that one of these factors may be confounding our findings." (PMID 28246524, 2017). "Although evidence is lacking of willin mutations in cancer, a tumour suppressor role for willin is suggested by ezrin’s antagonistic effects on willin in its ability to phosphorylate MST1/2." (PMID 27438856, 2016). "Ezrin, which is an actin scaffolding protein that complexes with the cytoplasmic tail of podocalyxin, also lined the invasive microlumens within the invasive nodules at the tumor/stromal interface in the MCF-7-podo condition (arrows)." (PMID 26796961, 2016).
tumor (continued). "Mesothelin, Ezrin and ENOA have also been linked to tumor metastasis and cancer progression." (PMID 26840568, 2016). "Moreover, knockdown TATDN1 also inhibited tumor growth and metastasis in a 95D mouse model in vivo by inhibiting β-catenin and Ezrin." (PMID 26943769, 2016). "MMP2/9, β-catenin and ezrin drives tumor progression and metastasis of cancer." (PMID 26943769, 2016). "There is increasing evidence to suggest that Ezrin regulates tumor progression." (PMID 26933912, 2016). "The membrane-cytoskeleton link organizer ezrin may be the most “dramatic” tumor marker, being strongly over-expressed in nearly one-third of human malignancies." (PMID 25915860, 2015). "Following antibody optimisation and staining, ezrin expression could be evaluated in tumours from 100/110 (90.9%) cases in Cohort I and 342/344 (99.4%) cases in Cohort II." (PMID 24885195, 2014). "Low cytoplasmic and membranous ezrin expression were associated with more advanced T-stage (p = 0.004, p < 0.001) and high-grade tumours (p = 0.025, p < 0.001), but not with age, sex, tumour location or smoking status." (PMID 25278252, 2014). "In tumours of pT2 stage and beyond cytoplasmic ezrin was not prognostic (data not shown), whereas loss of membranous ezrin was borderline prognostic (univariable and multivariable HR = 2.72, 95% CI 0.97-7.63)." (PMID 25278252, 2014). "In fact, we found several proteins possibly involved in actin cytoskeleton organization and cell-cell junction assembly, including talin-1, ezrin, plastin-3, fascin, catenin alpha-1, filamins A and B to be up-regulated in tumor tissues compared to control tissues." (PMID 24858105, 2014). "Ezrin therefore is significant in tumor progression, invasion and metastasis." (PMID 24959233, 2014). "Moreover, in that study, nearly all (103/104) tumours were reported to have positive membranous ezrin expression." (PMID 24885195, 2014). "We also recommend comparison of periocular BCC cases with BCC in other parts of the body regarding maspin and ezrin expression, due to the fact that region of tumor origin may affect its biological and clinical features." (PMID 25580109, 2014). "A diverse range of Src and ezrin expression was detected in the tumour tissues." (PMID 25231728, 2014). "In addition, the prognostic value of ezrin expression is validated in primary tumours, and the longitudinal expression of ezrin examined in a subset of primary and recurrent tumours (n = 28)." (PMID 25278252, 2014). "Another recent study on 104 bladder cancer cases of varying stages and grades, loss of membranous ezrin was found to correlate with adverse tumour characteristics, but the prognostic impact was not evaluated." (PMID 25278252, 2014). "Following antibody optimisation and staining, ezrin expression could be evaluated in 263/272 (96.7%) primary tumours and all 28 metastases." (PMID 25278252, 2014). "Recently, various tumor biomarkers are identified which have great importance in predicting clinical behavior of the cancers, among them, maspin and ezrin may be involved in BCC pathogenesis." (PMID 25580109, 2014). "The expression of both Src and ezrin KD were confirmed by immunostaining of tumour sections." (PMID 25231728, 2014). "ERM proteins, especially ezrin, have an important role in cancer invasion and metastasis through regulation of adhesion molecules, participation in cell signal transduction, and signaling to other cell membrane channels in the tumor." (PMID 24555568, 2014). "The herein observed discrepancy between ezrin expression in primary and metastatic tumours also indicates that the metastases may be the most suitable tissue for biomarker studies on patients with clinically advanced UC." (PMID 25278252, 2014). "Given the reported involvement of ezrin and ankyrin in cancer progression and of merlin in tumour suppression, we speculate that the spatial availability of CD44 to interact with specific cytosolic partners may differentially regulate cancer cell migration." (PMID 24512624, 2014).
tumor (continued). "The fractionational and confocal co-localization suggested the possibility that p-ezrin could be directly involved in the regulation of NHE1 activity in the tumor cells." (PMID 24086451, 2013). "Ezrin is a cytoskeletal protein involved in tumor growth and invasion." (PMID 23894313, 2013). "Interestingly, microscopic analyses also revealed ezrin and moesin expression in the stromal compartment of the BC tumour specimens and in its blood vessels." (PMID 23420497, 2013). "These functional aspects of ezrin are expected to promote tumor progression." (PMID 23357878, 2013). "On the basis of these data on ECM proteolysis together with reports in various tumor cell lines that p(T567)-ezrin (p-ezrin) drives invasion (see Introduction), we next tested the effect of these mutants on invasion using a 3D invasion assay where the cells must cross a thick layer of Matrigel." (PMID 24086451, 2013). "Altogether, these in vivo data predict that p-ezrin would make a novel tumor prognostic marker." (PMID 24086451, 2013). "Thus, ectopic expression of Y477F ezrin significantly reduces the frequency of lung metastatic lesions following orthotopic engraftment of AC2M2 tumor cells into the mammary fatpad." (PMID 22397367, 2012). "Given the role of Met in cell proliferation and tumorigenesis, our results may provide a mechanistic basis for understanding the role of ezrin in tumor progression." (PMID 22629406, 2012). "Fascin-1, ezrin or paxillin was mainly localized in the cytoplasm of tumor cells." (PMID 23209815, 2012). "Thus, phosphorylation of Y477 ezrin plays a key role in local invasion and metastasis from the primary tumor site." (PMID 22397367, 2012). "Ezrin is a cytoskeletal protein that is involved in tumor growth and invasion." (PMID 23039327, 2012). "We therefore sought to examine the role of Y477 phosphorylation in ezrin on tumor progression." (PMID 22397367, 2012). "EMR proteins share 75% sequence identity and thus it is logical to hypothesize that like ezrin, radixin and moesin might be involved in tumor cell migration." (PMID 22272721, 2012). "However, a significant reduction in the frequency of lung lesions, an indication of metastatic tumor load, was observed in Y477F ezrin clones compared to pCB6 control cells." (PMID 22397367, 2012). "Whereas orthotopically injected wild type AC2M2 tumor cells were found to infiltrate into the abdominal wall and visceral organs within three weeks, tumors expressing Y477F ezrin remained circumscribed, with little invasion into the surrounding stroma and abdominal wall." (PMID 22397367, 2012). "Furthermore, some studies suggested that EZR phosphorylation is not only present in the early stage of metastasis, but also late in tumor progression, at the leading edge of large metastatsic lesions." (PMID 23226966, 2012). "It has been suggested that Ezrin expression plays an important role in tumor metastasis." (PMID 23039327, 2012). "For example, it has been observed that ezrin promotes cell growth and may be key in tumor metastasis, while increasing evidence suggests that members of the 4.1 protein family act as tumor suppressors." (PMID 23170136, 2012). "Besides, berberine has been also shown to exert inhibitory effect on tumor cell invasion through the reduction of Rho kinase-mediated ezrin phosphorylation at threonine 567 or inhibition of PKC-mediated signaling pathway." (PMID 21738655, 2011). "We also established experimental and spontaneous mice models and showed that ezrin overexpression could enhance tumor metastasis in vivo, consistent with our observations in the cell motility/invasion and soft agar colony formation assays in vitro." (PMID 20569470, 2010). "In addition, in vitro study using DNA constructs including the wild type ezrin (wt-ezrin) and Tyr353 mutant ezrin (Y353-ezrin) were transfected into Hep3B cell to study its role in tumor invasion and differentiation." (PMID 19604375, 2009).
tumor (continued). "In addition, DNA constructs including the wild type ezrin (wt-ezrin) and mutant ezrin Tyr353 (Y353) were transfected into Hep3B cell to study its role in tumor invasion and differentiation." (PMID 19604375, 2009). "In addition to the detection of Pyk2 and FAK in the liver tumour and non-tumour tissues, the gene expression levels of ezrin and fibronectin, two potential metastatic genes, were also investigated according to patients' different expression levels of Pyk2." (PMID 17551499, 2007). "There is also increasing evidence that ezrin regulates tumour progression." (PMID 15987432, 2005). "In particular, the link between Ezrin and Phactr4 may be relevant to tumor pathogenesis." (PMID 40462895, 2025). "This could be explained by the association of high ezrin expression with the metastatic potential of cancer rather than its role in promoting tumor proliferation." (PMID 39827339, 2025). "Ezrin has been extensively studied in the field of tumorigenesis, with research focusing on its role in regulating cell migration, proliferation, differentiation, and apoptosis, as well as mediating cell-cell signaling to control tumor growth, differentiation, and apoptosis." (PMID 36968198, 2023). "Moreover, Ezrin (EZR) expression is upregulated in PDAC and is associated with tumor progression." (PMID 37444617, 2023). "However, we detected Ezrin mainly in immortal human tumor cell lines." (PMID 37928027, 2023). "Therefore, we presumed that AJAP1 may have prevented tumor malignant behavior by inhibiting Ezrin expression." (PMID 35311087, 2022). "Hence, we speculated whether CTCs and Ezrin, which are both closely related to tumor metastasis, are collectively responsible for predicting the metastatic process of PCa." (PMID 35156523, 2022). "Furthermore, ezrin also contributes to the cancer progression because of its role for the maintenance of migratory and the invasive capacity of tumor cells through the specific interaction with some tumor-associated plasma membrane proteins, leading to the metastatic behavior of tumor cells." (PMID 34577118, 2021). "However, depending on the polarization state, tumor-infiltrating macrophages also can exhibit pro-inflammatory, anti-tumorigenic activities, as considered below, and thus macrophage ezrin might exhibit anti-tumor activity in some circumstances." (PMID 33086476, 2020). "S100A4, cathepsin B, cyclin B1, Annexin A2, S100A10, TRIM21, 14-3-3 ζ/δ, and Ezrin may hence participate in tumor invasion depending on the grade of human CRCs, and protein upregulation during lymph node metastasis also suggests a positive correlation with metastasis in human CRCs." (PMID 32154176, 2020). "In addition, tumor suppressive role of MiR-183 was found to be implicated in the inhibition of Ezrin expression and suppression of MAPK/ERK activation, therefore, miR-183-Ezrin-MAPK/ERK axis was suggested to prevent progression and metastasis in OS." (PMID 32565738, 2020). "We therefore propose that tumor ezrin levels in BC, and most likely in other cancers of epithelial origin, would act as an independent biomarker in predicting relapse and recommend further development of therapeutic approaches to target ezrin in patients with high tumor ezrin levels." (PMID 30678714, 2019). "The positive ezrin and galectin-3 protein expressions in poorly differentiated patients were significantly higher than in the well-differentiated patients (all P<0.05), but were not correlated with age, menopausal status, histological type or tumor size (all P>0.05)." (PMID 28355349, 2017). "The results of several studies suggest that Ezrin may play a key role in tumor development, invasion, and metastasis, probably through regulation of adhesion molecules, participation in cell signal transduction, and signaling to other cell membrane channels in the tumor." (PMID 26933912, 2016). "Ezrin expression could be evaluated in tumours from 100 and 342 cases, respectively." (PMID 24885195, 2014).